EXO1 (exonuclease 1)
Description:
5'->3' double-stranded DNA exonuclease which may also possess a cryptic 3'->5' double-stranded DNA exonuclease activity. Functions in DNA mismatch repair (MMR) to excise mismatch-containing DNA tracts directed by strand breaks located either 5' or 3' to the mismatch. Also exhibits endonuclease activity against 5'-overhanging flap structures similar to those generated by displacement synthesis when DNA polymerase encounters the 5'-end of a downstream Okazaki fragment. Required for somatic hypermutation (SHM) and class switch recombination (CSR) of immunoglobulin genes. Essential for male and female meiosis.
Synonyms: hExoI; HEX1
Tractability: Small molecule: a structure with a bound ligand is known; it has a binding pocket of medium quality. Antibody: its Gene Ontology location is reachable by antibodies, with high confidence. PROTAC: ubiquitination databases record sites on it.
Target class: Enzyme; Hydrolase
Gene: Protein-coding gene on chromosome 1 (241,847,967 to 241,895,148, forward strand). Ensembl gene ENSG00000174371.
Subcellular location: Nucleus
Subcellular location (Human Protein Atlas): Nucleoplasm; Nuclear bodies
Pathways (Reactome):
DNA Repair: HDR through Homologous Recombination (HRR); HDR through Single Strand Annealing (SSA); Homologous DNA Pairing and Strand Exchange; Presynaptic phase of homologous DNA pairing and strand exchange; Processing of DNA double-strand break ends; Resolution of D-loop Structures through Holliday Junction Intermediates; Resolution of D-loop Structures through Synthesis-Dependent Strand Annealing (SDSA)
Disease: Defective HDR through Homologous Recombination Repair (HRR) due to PALB2 loss of BRCA1 binding function; Defective HDR through Homologous Recombination Repair (HRR) due to PALB2 loss of BRCA2/RAD51/RAD51C binding function; Defective homologous recombination repair (HRR) due to BRCA1 loss of function; Impaired BRCA2 binding to PALB2; Impaired BRCA2 binding to RAD51
Cell Cycle: G2/M DNA damage checkpoint
Gene Ontology:
Molecular function: 5'-3' DNA exonuclease activity; DNA binding; double-stranded DNA 5'-3' DNA exonuclease activity; flap endonuclease activity; protein binding; single-stranded DNA 5'-3' DNA exonuclease activity; 5'-3' exonuclease activity; exonuclease activity; RNA-DNA hybrid ribonuclease activity; catalytic activity; chromatin binding; DNA endonuclease activity; hydrolase activity, acting on ester bonds; metal ion binding; nuclease activity
Biological process: DNA recombination; DNA strand resection involved in replication fork processing; mismatch repair; DNA repair; t-circle formation
Cellular component: nuclear body; nucleoplasm; nucleus
Genetic constraint (gnomAD): Loss-of-function variants: 53 observed, 65.74 expected, observed/expected ratio (o/e) 0.81, 90% interval 0.65 to 1.01. The upper end of that interval is the gene's LOEUF score, 1.01, which puts it in group 4 of 6, group 1 being the genes least tolerant of losing a copy. Missense variants: 885 observed, 896.47 expected, observed/expected ratio (o/e) 0.99, 90% interval 0.93 to 1.04. Synonymous variants: 333 observed, 335.25 expected, observed/expected ratio (o/e) 0.99, 90% interval 0.91 to 1.09.
Gene-disease validity (ClinGen):
ClinGen rates the evidence that EXO1 causes each of these diseases.
Lynch syndrome (autosomal dominant): Refuted. An autosomal dominant hereditary neoplastic syndrome characterized by the development of colorectal carcinoma and a high risk of developing endometrial carcinoma, gastric carcinoma, ovarian carcinoma, renal pelvis carcinoma, and small intestinal carcinoma.
Homologues: Orthologues: chimpanzee EXO1 (99% identical), macaque EXO1 (96% identical), rabbit EXO1 (83% identical), pig EXO1 (82% identical), dog EXO1 (82% identical), guinea pig EXO1 (79% identical), rat Exo1 (75% identical), mouse Exo1 (73% identical), tropical clawed frog exo1 (48% identical), zebrafish exo1 (47% identical), Drosophila melanogaster tos (28% identical), Caenorhabditis elegans exo-1 (22% identical). Paralogues in human: GEN1 (15% identical), FEN1 (10% identical).
Diseases named in the same sentence as EXO1 in open-access papers:
EXO1 is named in the same sentence as 98 diseases in open-access papers, as found by Europe PMC text mining. Sharing a sentence is not in itself a finding about the gene and the disease. The quoted sentences say what the papers report.
breast cancer (35 papers, 2013 to 2025). A primary or metastatic malignant neoplasm involving the breast. "Previous studies have reported EXO1 expression in breast cancer to be associated with low methylation levels, and it has been found to be significantly enriched in the cell cycle pathway." (PMID 40092695, 2025). "High expression of EXO1 has been reported to be associated with poor prognosis in lung, prostate, and breast cancers." (PMID 35204661, 2022). "In one GWAS, a genetic marker in EXO1 (exonuclease 1) intron region, rs72755295, was identified to be associated with breast cancer in Caucasians." (PMID 36255267, 2022). "A previous genome-wide association study reports that rs72755295, a SNP locating at intron of EXO1 (exonuclease 1), is associated with breast cancer." (PMID 36255267, 2022). "Previous studies have shown that EXO1 is associated with the poor prognosis of patients with breast cancer, invasive ductal carcinoma, and gliomas." (PMID 35769911, 2022). "EXO1 polymorphism is linked to breast cancer susceptibility and the expression level is associated with poor prognosis." (PMID 33662042, 2021). "Then, we performed IHC to investigated if EXO1 protein levels were significantly associated with OS in breast cancer patients." (PMID 31777591, 2019). "High expression level of EXO1 protein was significantly associated with poor OS in breast cancer patients (p=0.03)." (PMID 31777591, 2019). "For survival analysis, Kaplan-Meier analysis showed that high EXO1 protein expression was significantly associated with decreased OS in breast cancer patients (p=0.03)." (PMID 31777591, 2019). "There are many candidate genes; CENF, KIF14, DTL, NEK2, CKS1B, ASPM and EXO1 each of which are significantly associated with poor clinical outcome in breast cancer patients." (PMID 25312014, 2014). "Another striking aspect of EXO1 module is that it includes all seven 1q candidate genes that were originally identified as genes associated with poor survival in breast cancer patients." (PMID 24147022, 2013). "The subsequent filtering with the combined p-value <0.005 across 6 datasets, yielded 7 candidate genes ASPM, KIF14, NEK2, DTL, CENPF, CKS1B and EXO1 that are significantly associated with poor clinical outcome of the breast cancer patients." (PMID 24147022, 2013). "All these show a strong association between EXO1 expression and poor clinical outcome in breast cancer patients." (PMID 24147022, 2013). "Some EXO1 variants have been associated with higher susceptibility for breast cancer." (PMID 39272813, 2024). "Elevated expression of EXO1 is associated with carcinogenesis and poor prognosis in breast cancer, and might act as a biomarker for breast cancer treatment." (PMID 36971680, 2023). "In the present research, population genetics and functional genomics approaches were utilized to explore the potential cis-regulatory variations for EXO1, which might further contribute to breast cancer predisposition." (PMID 36255267, 2022). "Since EXO1 is overexpressed in breast carcinoma samples, we hypothesized that the genetic variations in this locus might confer breast cancer risk by regulating EXO1 expression." (PMID 36255267, 2022). "In electrophoretic mobility shift assay, G of rs72755295 displays obviously higher binding affinity with nuclear protein than A. Our results indicated that rs72755295 is a cis-regulatory variation for EXO1 and might confer breast cancer risk besides rs4149909." (PMID 36255267, 2022). "On the other hand, EXO1 expression is observed to be significantly elevated in breast tumor tissue, hinting that the cis-regulatory variations for EXO1 might also contribute to breast cancer risk." (PMID 36255267, 2022). "In addition, it has been shown that the overexpression of EXO1 is associated with a poor prognosis in breast cancer." (PMID 34950206, 2021).
breast cancer (continued). "Therefore, the current identification of the consistently elevated expression of EXO1 gene and its association with poor survival in breast cancers in multiple co-horts is a significant observation." (PMID 24147022, 2013). "Further analysis on the features of EXO1 modular genes mirrored EXO1 in i) occurrence of enriched E2F binding sites in the promoter of EXO1 modular genes and ii) showing significant association with poor survival of the breast cancer patients." (PMID 24147022, 2013). "Together with Random Forest analysis and validation in an independent breast cancer cohort, these results identify N4BP2L2 as a robust suppressor of EXO1-induced HR deficiency." (PMID 41323735, 2025). "Another example is rs72755295, an intronic SNP in the exonuclease 1 (EXO1) gene, which enhances enhancer activity, upregulates EXO1 expression, and contributes to breast cancer susceptibility." (PMID 40429751, 2025). "Analysis of The Cancer Genome Atlas (TCGA) dataset revealed that EXO1 is highly expressed in basal-like breast cancer according to the PAM50 classification." (PMID 41323735, 2025). "This unbiased approach allowed us to identify a panel of five biomarkers, DNMT3B, EXO1, MCM10, CENPF and CENPE, that are robustly and significantly associated with disease-free survival prognosis in breast cancer." (PMID 37592220, 2023). "The EXO1 gene was investigated in a study using MDA-MB-231 breast cancer cells where an increase in gene expression was observed compared to the normal mammary epithelial cell line, MCF10A." (PMID 37374977, 2023). "These previous studies indicated that EXO1 rs1776148 and rs1047840 play an important role in lung cancer and breast cancer." (PMID 36277983, 2022). "For example, upregulated CCNE1, TTK and EXO1 displayed good diagnostic efficacy for screening breast cancer and BRCA1/2-mutant breast cancer." (PMID 31998560, 2020). "CCNE1, NPBWR1, A2ML1, EXO1 and TTK displayed good prognostic/diagnostic value for breast cancer and BRCA1/2-mutant breast cancer." (PMID 31998560, 2020). "Assessing the individual subtypes of breast cancer, it is clear that EXO1 and BLM were, in general, much more highly expressed than in normal breast tissue, whereas Trex1 expression was usually in a similar range." (PMID 28279982, 2017). "Since EXO1 expression is associated with the poor prognosis, there arises a question on EXO1 gene expression in the context of specific subtype(s)/group(s) of breast cancers." (PMID 24147022, 2013). "All these results demonstrate that MYC and E2F regulates the expression of EXO1 in breast cancer cells." (PMID 24147022, 2013). "The involvement of RAS/PI3K signalling cascade was confirmed owing to the reduction in EXO1 expression upon treatment with PI3K/AKT inhibitor LY-294002 in the breast cancer cell line MDA-MB-468." (PMID 24147022, 2013). "The candidate gene which is relatively underexplored in breast cancers is Exonuclease I (EXO1), a Rad2 family member possessing 5’-3’ exonuclease activity and well established for its role in mismatch repair and DNA recombination." (PMID 24147022, 2013). "Subsequently to address the association between EGFR and EXO1 gene expression, we treated EGFR positive breast cancer cell line, MDA-MB-468, with EGFR inhibitor, gefitinib." (PMID 24147022, 2013). "With evidences from the connectivity map and in-vitro gene expression analysis upon treatment with PI3K or RAS inhibitor, it seems possible to target PI3K or RAS in order to inhibit EXO1 modular expression in breast cancer cells." (PMID 24147022, 2013). "We addressed this by investigating the expression of EXO1 in 18 breast cancer transcriptome profiles that are available from microarray repositories GEO and Array Express." (PMID 24147022, 2013).
breast cancer (continued). "While the breast cancer candidacy of CENPF, KIF14, NEK2, DTL, CKS1B, ASPM and EXO1 genes have been identified earlier, there is only one prominent report indicating the candidacy of EXO1 in breast cancers and remains to be investigated." (PMID 24147022, 2013). "Motivated by the occurrence of underexplored candidacy of EXO1 from 1q, we investigated the upstream regulatory pathways and expression pattern across breast cancer sub-types." (PMID 24147022, 2013). "Analysis of the expression of EXO1 modular genes in a comprehensive panel of 51 breast cancer cell lines showed higher expression in basal and invasive breast cancer cell lines." (PMID 24147022, 2013). "This also illustrates the possible 1q amplification independent regulation of EXO1 module in breast cancers." (PMID 24147022, 2013). "This shows that apart from being a poor survival indicator, EXO1 expression in breast cancers is also indicative of cancers with elevated genomic instability." (PMID 24147022, 2013). "Using the concept of co-expression, we identified the common thread connecting EXO1 gene with other genes in breast cancer (EXO1 module) to be cell cycle progression and proliferation." (PMID 24147022, 2013). "Elevated expression of EXO1 in breast cancer patients with poor clinical outcome indicates the need for investigating the pathways and factors regulating EXO1 expression." (PMID 24147022, 2013). "Comparing EXO1 module with different sets of gene signatures revealed very less overlap with clinically used gene signatures like MammaPrint and Oncotype and other breast cancer derived prognostic gene expression signatures." (PMID 24147022, 2013). "A recent study showed the elevated expression of EXO1 in ductal carcinoma in situ samples and is the first hint wherein the role of EXO1 in breast cancer was revealed." (PMID 24147022, 2013). "In order to identify suitable cell lines for the in vitro experiments, expression of EXO1 across a panel of breast cancer cell lines was probed by western blotting and RT-PCR." (PMID 24147022, 2013). "In order to identify the possible upstream regulators of EXO1, gene signature based pathway activation pattern was investigated in the mRNA expression profiles of breast cancer samples." (PMID 24147022, 2013). "While EXO1 is a component gene of the PAM50 panel and is characteristically overexpressed in basal-like tumors, elevated expression was also observed in a subset of estrogen receptor (ER)-positive breast cancers, indicating a broader role for EXO1 beyond basal-like tumors." (PMID 41323735, 2025). "Yet, the impact of EXO1 overexpression on HR efficiency in estrogen receptor (ER)-positive breast cancer remains unclear." (PMID 41323735, 2025). "Moreover, high expression of EXO1 has been stated to be related to poor OS of breast cancer and hepatocellular carcinoma." (PMID 35837383, 2022). "In addition, we discovered six genes: CCNE1, CEP55, EGFR, EXO1, FGFR4, and MAPT associated with both types of breast cancer." (PMID 32724790, 2020). "We also assessed the involvement of EXO1 in DNA repair in breast cancer cells." (PMID 24147022, 2013). "The derived genes were analyzed in connectivity map and obtained a list of drugs that could inhibit the expression of genes which are expressed in breast cancer patients with elevated EXO1 expression." (PMID 24147022, 2013). "We delineated the upstream regulators of EXO1, an underexplored candidate gene in breast cancer." (PMID 24147022, 2013). "These show that EXO1 is regulated through RAS/PI3K/AKT signalling in breast cancer cells." (PMID 24147022, 2013). "EXO1 module represents a highly conserved set of interactions in breast cancer." (PMID 24147022, 2013).
breast cancer (continued). "While EXO1 overexpression has predominantly been associated with basal-like breast cancers, our analysis of the PAM50 data revealed that EXO1 is also elevated in a subset of ER-positive tumors, suggesting that EXO1’s involvement in HR deficiency might extend beyond the basal-like subtype." (PMID 41323735, 2025). "Given that homologous recombination (HR) deficiency is commonly associated with BRCA1 loss and basal-like breast cancer, we hypothesized that ER-positive breast cancer—where BRCA1 is typically intact—would provide a valuable model to study the effect of EXO1 overexpression on HR." (PMID 41323735, 2025). "The high expression of EXO1 in breast cancer and lung cancer may promote tumor development." (PMID 35449547, 2022). "Importantly, EXO1 expression is indicative for all these features in breast cancers." (PMID 24147022, 2013). "We observed a striking concordance between the expression pattern of EXO1 and RAS activation pattern in breast cancer cell lines reported earlier." (PMID 24147022, 2013). "As expected, EGFR inhibition resulted in reduced expression of EXO1 in MDA-MB-468, thereby illustrating the involvement of EGFR/RAS cascade in the regulation of EXO1 gene expression in breast cancer cells." (PMID 24147022, 2013). "EXO1 expression was also positively correlated with survival in breast cancer but not in ovarian cancer." (PMID 35642638, 2022). "The significance of this regulation of Exo1 by FOXM1 in DDR is highlighted by the revelation that FOXM1 modulates the sensitivity to the DNA-damaging agents, cisplatin and doxorubicin, through regulating EXO1 in ovarian and breast cancer, respectively." (PMID 29180117, 2018). "In the current integrative genomic investigation, analysis of EXO1 gene expression across various groups and subtypes of breast cancer reveal EXO1’s higher expression in higher grade, basal and ER negative subtypes." (PMID 24147022, 2013). "These analyses revealed five genes, DNMT3B, EXO1, MCM10, CENPF and CENPE, that are normally not expressed in healthy breast tissue but become frequently activated in breast cancers." (PMID 37592220, 2023). "FOXM1 regulates XRCC1 and BRCA2 in HER positive breast cancer, in triple-negative breast cancer, however, FOXM1 transactivates EXO1 and PLK4 in response to doxorubicin." (PMID 24824601, 2014).